BAK1P1 (BCL2 antagonist/killer 1 pseudogene 1)
Synonyms: BAK2; formerly BCL2L7P1
Gene: Processed pseudogene on chromosome 20 (32,690,180 to 32,690,815, reverse strand). Ensembl gene ENSG00000175730.
Diseases named in the same sentence as BAK1P1 in open-access papers:
BAK1P1 is named in the same sentence as 1 disease in open-access papers, as found by Europe PMC text mining. Sharing a sentence is not in itself a finding about the gene and the disease.
BAK1P1 shares sentences with these, for which no sentence is quoted: Immunodeficiency (1 paper).